SOX4 (SRY-box transcription factor 4)
Diseases named in the same sentence as SOX4 in open-access papers (continued):
Sharing a sentence is not in itself a finding about the gene and the disease.
breast carcinoma (continued). "In breast cancer, the developmental transcription factor SOX4 can mediate TGF-β-induced action and promote EMT, tumor progression, and metastasis in breast cancer." (PMID 34335834, 2021). "Functional experiments demonstrated that knockdown of SOX4 suppressed EMT and CSC phenotypes of breast cancer cells through TGF-β/SMAD pathway, which was consistent with the inhibitory effects by overexpression of miR-30a." (PMID 34234874, 2021). "In other breast cancer cells, MDA-MB-231, TRPM7 contributes to maintaining a mesenchymal-like phenotype by tensional regulation of the SRY-Box Transcription Factor 4 (SOX4), a recently identified regulator of EMT in breast cancer cells." (PMID 34944940, 2021). "Although it has been reported that both miR-30a and SOX4 are involved in regulation of EMT and stemness, we are the first to report that miR-30a targets SOX4 to inhibit EMT and CSC phenotypes in breast cancer through TGF-β/SMAD pathway." (PMID 34234874, 2021). "A caveat to most of these studies is that it has been shown that SOX4 regulates EMT in vitro and mammary tumor progression in vivo." (PMID 34584219, 2021). "For example, SOX4 is a tumor promoter shown to contribute to drug resistance and progression in cervical cancer and regulate the EMT program in breast cancer." (PMID 32550913, 2020). "SOX4 is a pivotal inducer of EMT in human malignancies contributing to metastasis, which has been validated in various tumours, such as breast cancer, gastric cancer, colon cancer and liver cancer." (PMID 32924268, 2020). "We performed IHC and detected the SOX4 and CXCR7 expression in all the 36 pairs of human primary breast carcinomas and their corresponding lymph node metastases in a tissue chip slide." (PMID 33005101, 2020). "The last example is ARNILA, which competes with SOX4 on sponging of miR-204 resulting in increased SOX4 and resultant EMT and metastasis in breast cancer." (PMID 33224198, 2020). "ChIP analysis revealed that EZH2 can directly bind to SOX4 promoter regions and induce trimethylation of H3K27 in breast cancer cells." (PMID 31557401, 2019). "Our results showed that SOX4 knockdown compromised, at least partially, the effects of LINC01133 on breast cancer invasion and cell viability." (PMID 31557401, 2019). "Gene set analysis revealed that in human breast cancer cell lines the expression of these seven genes (MUC1, PLAU, FABP7, SPARC, HAS2, HAS3, SOX4) are higher in basal-B subtype compared to other subtypes." (PMID 29435170, 2018). "(C–E) Kaplan-Meier curves for cumulative (cum) survival for patients with high or low nuclear SOX4 expression for the total cohort, ILC and IDC breast cancers." (PMID 30507376, 2018). "We also used immunofluorescence to determine the effects of CXCL1 on SOX4 signaling, and found that after CXCL1 treatment, SOX4 expression significantly increased in the nucleus of both breast cancer cell lines." (PMID 30158589, 2018). "Depletion of SOX4 in MDA-MB-231 cells reduces ET-1 expression and decreases tumor vascularization and metastasis in a xenograft mouse model of breast cancer." (PMID 30507376, 2018). "For instance, Sox12, together with Sox11 and Sox4, is a member of the SoxC TF family, of which Sox4 has an established role in EMT and breast cancer progression." (PMID 29079737, 2017). "To provide a mechanistic explanation of the inhibitory activities of Flavipin on breast cancer cells, we examined selected anti-apoptotic (Bcl2), adhesion (ITGA4) and pro-metastatic (Sox4) markers." (PMID 27907195, 2016). "SOX4 has been shown to function cooperatively with SOX11 during neuronal development and is also a regulator of EMT in breast cancer." (PMID 26894864, 2016).
breast carcinoma (continued). "We thank J. Massague and S. Tavazoie for MCF7, MDA231-Par, its metastatic derivatives and CN34-LM1 cell line, A. Dent for c-JUN, R.A. Weinberg for SOX4 construct, S.J. Kang and F. Miller for RAW cells and mouse mammary tumour cell lines, W.-D." (PMID 27982029, 2016). "Comparing to Srsf3 WT liver cancer, Srsf3 KO significantly increases Sox4, E2f1, Trpv4, Trim6, and Myc expression, but does not so in Erbb2 breast cancer." (PMID 40568073, 2025). "that Sox4 regulates EMT via the epigenetic modifier Ezh2, promoting breast cancer." (PMID 40978031, 2025). "Importantly, the inhibition of SOX4 and FGFR1 translation by zotatifin was observed in both mouse tumors and human breast cancer cell lines, indicating the conserved regulation of these genes by eIF4A." (PMID 37874652, 2023). "For instance, SOX4 overexpression is in favor of breast cancer progression and EZH2 reduces its expression by binding to the promoter, leading to a decrease in invasion and migration of breast cancer cells." (PMID 35236381, 2022). "Furthermore, SOX4 stimulates PI3K/AKT signaling in multiple human diseases, including acute myeloid leukemia, breast cancer, pancreatic cancer and prostate cancer." (PMID 35294319, 2022). "SOX4 is recognized as a master regulator of cell proliferation and metastasis in several cancer types, while SOX11 recognized as a poor prognosis marker in lymphoma and breast cancer subtypes." (PMID 35529852, 2022). "As a member of the SOX transcription factor family, SOX4 has been shown to have an essential relationship with not only normal development but also cancers, such as lung cancer, breast cancer, leukemias, glioblastoma, and medulloblastoma." (PMID 36428735, 2022). "Given that our data identifies SOX4 and SMARCA4 as key modulators of TGFBR2 expression and PI3K activity in basal-like breast cancer, it remains to be determined if aberrant TGFBR2 activity can also regulate a similar resistance mechanism to PI3K-family inhibitors in TNBC patients." (PMID 33837205, 2021). "Profiling of the drug-able kinome in addition with transcriptome analyses suggest that SOX4 alone and in combination with SMARCA4 may modulate unique gene expression programs that contribute to breast-cancer genesis, progression, and response to therapy." (PMID 33837205, 2021). "Especially, Snail has been reported to repress the transcription of E‐cadherin and SOX4 could regulate EMT with the same mechanism of Snail 47, they might have interaction through the process of EMT in breast cancer." (PMID 34234874, 2021). "It has been reported that SOX4 is upregulated in various malignancies, including HCC, pancreatic cancer, bladder carcinoma, prostate cancer, breast cancer, colorectal cancer, gastric cancer and melanoma 11, 12, 14, 32, 40-44, raising the potential of this gene as a diagnostic marker." (PMID 33995626, 2021). "Smad cofactors that have been reported to be involved in TGF-β-induced cell motility or invasion include JunB in breast cancer cells, Olig1 in NMuMG cells, and Sox4 in nontransformed human mammary epithelial cells." (PMID 33741342, 2021). "Importantly, as shown by our IHC studies, both SOX4 and CXCR7 are strongly expressed in human primary breast cancer cells and the metastatic foci in lymph nodes." (PMID 33005101, 2020). "Next, we examined the RNA level of SOX4 and LINC01133 in 40 clinical breast cancer samples." (PMID 31557401, 2019). "Moreover, we revealed that LINC01133 inhibited invasion and metastasis in breast cancer, partly through binding with EZH2 to mediate SOX4 transcriptional inhibition." (PMID 31557401, 2019). "PTPRN2, MERTK, TNC and SOX4 were identified to be targets of miR-335, AIB1 and CCND1 were the targets of miR-17-5p, and H-RAS and HMGA2 were verified as targets of let-7 in breast cancer." (PMID 30309377, 2018).
breast carcinoma (continued). "Taken together, our results indicated that TAMs/CXCL1 promotes breast cancer metastasis via NF-κB/SOX4 activation, and CXCL1-based therapy might become a novel strategy for breast cancer metastasis prevention." (PMID 30158589, 2018). "Researchers have shown that Sox4 could promote EMT properties, the number of CD44high/CD24low population, and sphere-forming ability in breast cancer cells." (PMID 26933999, 2016). "The current results, for the first time, demonstrated that toxic and non-toxic Ahr agonists suppressed breast cancer metastasis through triggering the transcription of SOX4-targeting miR-212/132 cluster." (PMID 26377202, 2015). "miR-335 appears to control growth by blocking cell proliferation by targeting certain genes; e.g., RASA1 in rat epididymal development, SP1 and Bcl-w in non-small cell lung cancer, SOX4 and TNC in breast cancer, ROCK1, MAPK1, and LRG1 in neuroblastoma, and Rb1 in U2OS osteosarcoma cells." (PMID 26204513, 2015). "SOX4 induces EMT and breast cancer progression by cooperating with oncogenic Ras." (PMID 25644061, 2015). "According to a recent study, SOX4 and SOX11 could promote breast cancer metastasis." (PMID 39741182, 2025). "These included genes such as SCUBE3, MARCKSL1 and PGK1 in lung cancer, SOX4 and GNAS in breast cancer and hepatocellular carcinoma, HEG1 in hepatocellular carcinoma, PLS3 in pancreatic adenocarcinoma, FBN1 and SPARC in gastric cancer and CST1 in gastric cancer and breast cancer." (PMID 40430098, 2025). "Whether SOX4 can also inhibit tRNA production in breast cells was not tested, but it is commonly overexpressed in breast cancer, where it can stimulate invasion, and it correlates significantly with parameters of poor prognosis." (PMID 37509247, 2023). "SRY-related HMG-box 4 (Sox4), one of the members of the SRY-related HMG-box family TFs has been shown to play significant role during EMT in various cell types including mammary epithelial cells, breast cancer cells, gastric cancer cells, prostate cancer cells, renal cancer cells etc." (PMID 34708244, 2022). "Finally, SOX4 is a known driver of EMT and metastatic potential in breast cancer." (PMID 30670058, 2019). "Moreover, SOX4 protein expression in both primary and metastatic tumor-tissue of patients with breast cancer has not been systematically studied." (PMID 30507376, 2018). "To investigate whether SOX4 expression is also associated with increased angiogenesis in patients with human breast cancer, we examined CD34 expression (a marker for small and newly formed blood vessels) in 17 SOX4-low (SOX4LO) and 17 SOX4-high (SOX4HI) ductal carcinomas from our cohort." (PMID 30507376, 2018). "For example, elevated Sox4 expression has been reported in a wide variety of tumors, including leukemia, colorectal cancer, lung cancer and breast cancer, suggesting a fundamental, yet not necessarily pro-proliferation, role in the development of these malignancies." (PMID 24231253, 2013). "In summary, the miR-30a/SOX4 double negative feedback loop firstly identified here is modulated by disulfiram and regulates EMT and stem cell-like phenotypes through TGF-β/SMAD signaling pathway in breast cancer." (PMID 34234874, 2021). "Our results suggest that the miR-30a and SOX4 double negative feedback loop is modulated by disulfiram and plays a key role in the regulation of EMT and stem cell-like phenotypes via TGF-β/SMAD signaling pathway in breast cancer." (PMID 34234874, 2021). "With a series of experiments, we eventually elucidated that miR-30a targeted the 3'UTR of SOX4 and formed a double-negative loop with SOX4 to inhibit EMT and stem cell-like phenotypes in breast cancer via blockade of TGF-β/SMAD signaling pathway both in vitro and in vivo." (PMID 34234874, 2021). "In addition, it was recently shown that sox4 potentiates the RAS-induced tumorigenesis in non-transformed breast cells and reduces the potential of highly metastatic derivatives of breast cancer." (PMID 24231253, 2013).
breast carcinoma (continued). "Therefore, the observation that SOX4 and SMARCA4 mediate PI3K activity through TGFBR2 expression identifies a novel and direct role for TGFBR2 in activating noncanonical PI3K signaling in basal-like breast cancer." (PMID 33837205, 2021). "Moreover, knockdown of Sox4 reversed the effect of miR-381-3p depletion on breast cancer proliferation and invasion in MCF7 cells, whereas knockdown of Twist1 reversed the effect of miR-381-3p depletion on breast cancer invasion, but not altered the proliferation in MCF7 cells." (PMID 34362391, 2021).
gastric cancer (51 papers, 2012 to 2025). A primary or metastatic malignant neoplasm involving the stomach. "Herein, we collected 54 normal gastric tissues and 54 gastric cancer tissues to analyze the association of miR-204 and SOX4 expression." (PMID 28133610, 2017). "And we for the first time document that SOX4 was associated with lymph node metastasis and tumor stages of gastric cancer." (PMID 28133610, 2017). "SOX4 was also reported to be one target of miR-204 in renal cancer, T-cell acute lymphoblastic leukemia, and H. pylori-associated gastric cancer." (PMID 28133610, 2017). "In a word, we documented miR-204 suppressed proliferation and metastasis of gastric cancer cells and found miR-204 and SOX4 were negatively correlated and associated with clinicopathological parameters in gastric cancer patients." (PMID 28133610, 2017). "Although several studies have associated SOX4 expression with shorter survival in prostate cancer, gastric cancer, and colon cancer, this is the first to demonstrate the correlation between SOX4 expression and treatment failure in OSCC." (PMID 26555193, 2015). "The epigenetic repression of miR-129-2 leads to overexpression of SOX4 and the up-regulation of SOX4 was inversely associated with the epigenetic silencing of miR-129-2 in gastric cancer." (PMID 25344911, 2014). "Most importantly, miR-129 downregulation is associated to SOX4 overexpression in endometrial and gastric cancers." (PMID 24093088, 2013). "Getting together, in miR-204 regulation pathway, USP47, RAB22A, SIRT1, Snai1, and so forth and SOX4 may play an associating role contributing to gastric cancer progressing." (PMID 28133610, 2017). "High SOX4 expression has been associated with better prognosis for patients with hepatocelluar carcinoma, medulloblastoma, and bladder cancer, but with shorter survival in prostate cancer, gastric cancer, and colon cancer." (PMID 26555193, 2015). "circ-DONSON facilitates the transcriptional activation of SOX4 by interacting with the nucleosome remodeling factor complex at the SOX4 promoter region, contributing to gastric cancer progression." (PMID 41550639, 2025). "A mechanistic study showed that ALKBH5-mediated m6A modification of circFOXP1 promoted gastric cancer progression by regulating SOX4 expression and sponging miR-338-3p, resulting in a promoting effect on GC progression." (PMID 38745044, 2024). "Previous studies have shown that the NURF complex can be recruited to the promoter region of SOX4 to participate in the maintenance of gastric cancer stem cell properties." (PMID 36967443, 2023). "In STAD, MIR4435-2HG is engaged in the development, metastasis and EMT of gastric cancer cells through mediating the miR-138-5p/Sox4 axis." (PMID 35574385, 2022). "In gastric cancer 31 and cervical cancer 30, SOX4 is identified a target of miR-211, and promotes cells invasion." (PMID 35912006, 2022). "A previous report showed that circ-DONSON regulates SOX4 expression and facilitates gastric cancer cell growth and invasion." (PMID 34853591, 2021). "For example, circ-DONSON facilitates the proliferation and invasion of gastric cancer cells by activating NURF complex-mediated transcriptional expression of SOX4." (PMID 34060415, 2021). "SOX4 was overexpressed in gastric cancer, and enforced expression of SOX4 promoted TGF-β-induced EMT and stem cell characteristics in gastric cancer through activation of the Wnt pathway." (PMID 33854048, 2021). "Overexpression of SOX4 promotes epithelial-mesenchymal transition and stem cell characteristics of gastric cancer cells." (PMID 34853591, 2021). "Our data provide the new insight into the mechanism by which MIR4435-2HG contributes to EMT and malignant progression of gastric carcinoma by targeting miR-138-5p/Sox4 axis." (PMID 34532282, 2021). "si-MIR4435-2HG#1 was co-transfected with anti-miR-138-5p and pcDNA-Sox4 to determine that MIR4435-2HG controls EMT in gastric carcinoma cells through miR-138-5p/Sox4 axis." (PMID 34532282, 2021).